EZH2 (enhancer of zeste 2 polycomb repressive complex 2 subunit)
Diseases named in the same sentence as EZH2 in open-access papers (continued):
Sharing a sentence is not in itself a finding about the gene and the disease.
tumor (continued). "NK cells are known to mediate tumor cell lysis and we observed association of increased NK cell infiltration with increased TUNEL staining in EZH2 inhibitor-treated xenografts." (PMID 30692641, 2019). "A normalization of the RNA sequencing (RNA-seq) reads over vehicle-treated controls revealed a striking number of DRGs in tumor cells treated with Ezh2 inhibitors." (PMID 30487290, 2018). "There are few scientific studies connecting hypoxia, HIF-1, and EZH2 during tumor formation or tumor progression." (PMID 30510924, 2018). "We demonstrated that Ezh2 mRNA expression is significantly correlated with tumor stage and invasion." (PMID 29335012, 2018). "The results in the IHC cohort showed that Ezh2 protein expression was also correlated with the tumor size (P = 0.018), lymphatic invasion (P = 0.027) and TNM stage (P = 0.038)." (PMID 29335012, 2018). "EZH2 expressed by tumour cells has been reported to subvert the cytokine milieu, limit the recruitment of Th1 effectors, and ultimately favour immunoevasion." (PMID 30510965, 2018). "HOTAIR regulated cell cycle through interacting with EZH2 and affected tumor growth of GBM in vivo and in vitro." (PMID 30376874, 2018). "The tumor-promoting effect induced by ATX loss is mainly mediated via EZH2 upmodulation; in line with this finding, these tumors are sensitive to EZH2 inhibitors." (PMID 30060526, 2018). "Recently, a study uncovered that tumor-infiltrating Tregs (TI-Tregs) acquire pro-inflammatory functions through pharmacological or genetic suppression of the activity of EZH2." (PMID 30558227, 2018). "Simultaneous analyses of the EZH2 expression and the methylation of tumor suppressor genes is important to predict tumorigenesis and the development of future targeted therapy." (PMID 30469511, 2018). "As anticipated, we observed a global decline in binding peak events across the genome including at the transcriptional start sites of genes in Ezh2-null tumours." (PMID 29959321, 2018). "EZH2 is the enzymatic subunit of Polycomb repressive complex 2 (PRC2), which methylates H3K27, resulting in silence of the associated tumor suppressor genes." (PMID 30100882, 2018). "The results of EZH2 high activation seem to be context specific: the molecule can transcriptionally silence DNA-damage repair genes, pRB tumor suppressor and lineage specification genes, all leading to cancer as a common consequence." (PMID 29615825, 2018). "Together, we conclude that CARM1-mediated methylation of BAF155 drives a switch from BAF155 to EZH2 at the promoters of the BAF155/EZH2 target tumor suppressor genes." (PMID 29434212, 2018). "In fact, recent works have demonstrated that inhibition of EZH2, both genetically and pharmacologically, leads to suppression of cell growth, increased apoptosis, inhibition of tumor sphere formation and radiosensitization in AT/RT cell lines." (PMID 29487714, 2018). "What is more, EZH2 has decisive roles in immune cells (for example, T cells, NK cells, dendritic cells and macrophages), which are essential components in tumor microenvironment." (PMID 29556394, 2018). "Overall, EZH2 expression levels were elevated in parallel with tumour stage (Kruskal-Wallis test p = 0.001) and were also increased in MIBC compared with NMIBC according to the Mann-Whitney test (p = 0.027)." (PMID 30542123, 2018). "Most importantly, a pharmacological approach based on daily dosing of GSK126, a clinically relevant Ezh2 inhibitor, also promoted a moderate and significant tumor growth inhibition and extension in survival." (PMID 30487290, 2018). "Murine cell-based data as well as resultsfrom primary human tumours has provided evidence forthe activation of Ezh2." (PMID 29845782, 2018).
tumor (continued). "Our clinical analysis found that Ezh2 overexpression was significantly correlated with GC tumor lymphatic invasion." (PMID 29335012, 2018). "While many of these factors were previously known to be downstream of EZH2 inhibition, the combination with panobinostat illuminated an enhanced augmentation of tumor-promoting pathways as well as several enriched results unique to the combination." (PMID 29774113, 2018). "EZH2, the catalytic subunit of PRC2, is involved in cell proliferation, cell differentiation and apoptosis, and EZH2 deregulation participates not only in tumorigenesis, tumor progression, and tumor metastasis but alsoin tumor microenvironment modulation." (PMID 29316949, 2018). "Although it is reported that Ezh2 regulates Cdkn2a and Cdkn1c loci in tumor cell lines, the involvement of Ezh2 in activation induced CD8+ T cell cycle progression and apoptosis has not been fully characterized." (PMID 29632530, 2018). "Total RNA was extracted from the tumor tissues and RT-qPCR illustrated that GA decreased EZH2 mRNA expression and increased miR-101 expression, but these effects were significantly suppressed by knockdown of GAS5." (PMID 29445179, 2018). "Specifically, the authors found that EZH2 inhibition induces the expression of epithelial tumor suppressor genes including CDH1, EMP1, VCAN, EPHB2, and ENPP1, which enhance MM cells adhesion properties." (PMID 30761216, 2018). "Accumulating studies indicate that inhibition of EZH2 by small molecular inhibitors or gene knockdown results in reduced cancer cell growth and tumor formation." (PMID 29556394, 2018). "Since complete ablation of Ezh2 reduced tumour focality and proliferation, animals were killed at an endpoint defined by total tumour volume to confirm that metastatic phenotypes were exclusive of the reduced proliferative capacity of Ezh2-null tumours." (PMID 29959321, 2018). "Wilson and colleagues observed that loss of SMARCB1 (SNF5) triggers EZH2 expression, broad H3K27-trimethylation, subsequent repression of Polycomb target genes finally resulting in tumor formation." (PMID 30138427, 2018). "Previous studies have reported that high expression of EZH2 was found in various kinds of cancers, which contributed to tumor progression and poor prognosis." (PMID 30120321, 2018). "Upon DZNepA treatment (1 mg/kg body weight, 20 days), expression of EZH2 was reduced by 48% and a reduction of 36.5% was observed in the expression of Ki67, which clearly indicated the potential of DZNepA in reducing the tumor burden." (PMID 29396474, 2018). "A second recent study confirmed and extended these findings, showing that about 80% of SCCOHT tumor samples exhibit strong EZH2 expression by immunohistochemistry; re-expression of SMARCA4 in these cells reduced EZH2 expression." (PMID 29389895, 2018). "LBH589, an HDAC inhibitor indirectly causes degradation of EZH2 through interference with protein chaperone function and reactivated the expression of genes repressed by PRC2 in vitro and in vivo, reduced tumor load, and increased overall survival." (PMID 30761216, 2018). "We also reveal that the synergistic anti-tumor effect of elemene and gefitinib was largely mediated their regulation of enhancer of zeste homolog 2 (EZH2), an oncogenic histone methyltransferase and gene transcriptional regulator." (PMID 30555330, 2018). "Inhibitors targeting EZH2 increase the expression of CTAs and enhance the immunogenicity of the tumor cells." (PMID 30558227, 2018). "In accordance with the reported role of Ezh2 in promoting growth, our results indicate that Ezh2 stimulated tumor growth." (PMID 29335012, 2018). "In NSCLC, it is proposed that when Ezh2 is overexpressed, cells fail to transcribe tumor suppressor genes and microRNAs that would otherwise restrict tumor growth." (PMID 30487290, 2018).
tumor (continued). "let-7, initially increased by chemotherapeutic treatments, can decrease de novo because of tumour acquired resistance following, for example, irradiation or cisplatin therapy that likely increases EZH2 in human non-small cancer lung cells (NSCLCs)." (PMID 29853899, 2018). "Unsurprisingly, the biological functions of EZH2 in different kinds of tumor cells are under intense investigation." (PMID 29556394, 2018). "In RCC cells, MALAT1 was positively regulated by VHL pathway through c-FOS transcription factor and promoted EMT features of tumor cells in a PRC2-dependent manner, since EZH2 depletion inhibited MALAT1-dependent tumor-promoting activity." (PMID 29739426, 2018). "We further confirmed Foxc1 upregulation in the epithelial compartment of Ezh2-null tumours by qPCR and immunoblotting." (PMID 29959321, 2018). "Even in the monophasic and biphasic subtypes, patients with high EZH2 score was characterized by high proliferation rate, large tumor size, distant metastasis and poor outcomes." (PMID 30120321, 2018). "Ezh2 mRNA expression levels in tumor tissues were categorized as low or high relative based on the median." (PMID 29335012, 2018). "In contrast, in tumor vasculature, high nuclear EZH2 staining paralleled a significant reduction in VEC and Claudin-5, whereas PECAM1 expression was unaltered (lower, and 8C)." (PMID 29233846, 2018). "The decrease in weights of BalB/c nude mice and tumor diameter were significantly different between the EZH2 knockdown group and NC group." (PMID 29445149, 2018). "3-deazaadenosine A (DZNep) is a non-specific EZH2 inhibitor which decreases the protein level of EZH2 and the H3K27me3 marks, thereby exhibiting anti-tumor effects in various malignancies." (PMID 29556394, 2018). "EZH2 is involved in the pathogenesis of MM as a tumor suppressor and also has a role in drug resistance and maintenance of stem cell-like populations." (PMID 30555699, 2018). "An extensivenumber of studies have shown that many tumor suppressor genes, including miRNAs are suppressed by EZH2 in malignancies andthat EZH2 dysregulation plays a crucial role in carcinogenesis." (PMID 29316949, 2018). "EZH2 plays a role in tumor invasiveness, colony formation and migration and are related to the expression of CSC-related genes (CD44, KLF4, OCT4 and ABCG2)." (PMID 30072631, 2018). "Regarding EZH2 as a binary variable, high EZH2 expression was seen in 76.7% of tumours and in 4.5% of benign urothelium." (PMID 30542123, 2018). "EZH2 is overexpressed in many cancers in which it either plays a role as an oncogene, as seen in most cases studied, or as a tumor suppressor." (PMID 29178021, 2018). "EZH2 upregulation was significantly correlated with recurrence (p < 0.001) and the methylation index of tumor suppressor genes (p < 0.05)." (PMID 30469511, 2018). "In fact, Ezh2 regulates the expression of various EMT-related genes in various cancer types, suggesting that Ezh2 is required for EMT during tumor progression." (PMID 29335012, 2018). "Specifically, let-7b was previously reported to inhibit the growth of tumor stem cells by regulating EZH2." (PMID 30324582, 2018). "The context-dependent nature of Ezh2 function has also been proposed to be determined by the cell of origin and/or early transformation events undertaken by a tumour cell." (PMID 29959321, 2018). "Collectively, we herein provided the compelling evidences to show that combination of elemene and gefitinib had a greater anti-tumor activity, which was largely through its regulation of EZH2." (PMID 30555330, 2018). "To account for non–cell-autonomous factors, we co-cultured tumor cells with the macrophage cell line Raw267.4 in the presence of short-term Ezh2 inhibition and further mimicked proinflammatory stimulation using LPS." (PMID 30487290, 2018).
tumor (continued). "For instance, it has been suggested that the inhibition of the histone H3K27 demethylase UTX shows promising antitumor effects in T-ALL, while the activity of H3K27 methyltransferase EZH2 acts as tumor suppressor in ALL mouse models." (PMID 30213075, 2018). "This anti-tumor capability was partially at least, through the disruption of EZH2-dependent oncogenic pathway." (PMID 30555330, 2018). "Our cross-examination revealed that ~22% of differentially upregulated genes in Ezh2-null Tet-ON PyVmT tumours were H3K27me3 targets." (PMID 29959321, 2018). "This work led to the identification of a Luminal B-specific anti-metastatic transcriptional program centred on the master transcriptional regulator FOXC1, which is silenced in these tumours in an Ezh2-dependent manner." (PMID 29959321, 2018). "EZH2 overexpression was sufficient to induce tumor formation in mice, suggesting it is a true oncogene." (PMID 30555699, 2018). "EZH2, through its catalytic activity, has been shown to be a tumor promoter, because it can repress tumor suppressors such as p16Ink4a and p14ARF." (PMID 29874793, 2018). "In summary, we demonstrated that Ezh2 is overexpressed in primary GC and its expression is correlated with the tumor burden and clinical outcome." (PMID 29335012, 2018). "EZH2 is also known to interact with tumor suppressor miRNAs, which contributes to MM cell proliferation and drug resistance." (PMID 30555699, 2018). "Our network analysis largely corroborated findings that EZH2 inhibition leads to a robust upregulation of tumor suppressors and concomitant downregulation of oncogenic pathways." (PMID 29774113, 2018). "Aberrant EZH2 expression and activity in immune cells in the tumor microenvironment affects tumor progression and therapy." (PMID 29556394, 2018). "We chose xenograft nude mice model to study the effect of NIC on tumor aggressiveness/implantation by modulating EZH2 expression and role of DZNepA in reducing NIC-induced increased tumor burden." (PMID 29396474, 2018). "By interrogation of our ChIP-Seq data to identify genes losing H3K27me3 in Ezh2−/− compared to Ezh2+/+ tumours, we confirmed that Foxc1 is directly targeted by Ezh2-mediated H3K27me3." (PMID 29959321, 2018). "This reveals that EZH2 can act as both an oncogene and a tumour suppressor gene, depending on the context." (PMID 29759978, 2018). "The observed selectivity correlates with reactivation of EZH2 target tumor suppressor genes in a CARM1-dependent manner." (PMID 29434212, 2018). "EZH2 has also been shown to regulate the function of Tregs, dendritic cells and macrophage, all of which are critical parts of tumor microenvironment." (PMID 29556394, 2018). "In specific cancer types, downregulation of these microRNAs leads to EZH2 overexpression and subsequent H3K27me3 accumulation to promote tumor progression." (PMID 29556394, 2018). "As far as we know, all the published studies have confirmed that the expression levels of EZH2 protein were increased in tumours compared with normal urothelium." (PMID 30542123, 2018). "The first was at 12 d after the introduction of tumor cells, an asymptomatic stage in which Ezh2 depletion is tumor suppressive and representing half of the median survival time in control animals (hereafter referred to as OS50)." (PMID 30487290, 2018). "Inhibition of EZH2 in HSPCs gives rise to increased NK precursors and mature progeny displaying enhanced cytotoxicity against tumor cells." (PMID 29556394, 2018). "We detected the relative EZH2 protein expression levels by immunohistochemistry in tumour specimens from a cohort of 189 Chinese UC patients." (PMID 30542123, 2018). "In tumor cells, EZH2 mediates the silencing of anti-metastatic genes, including E-cadherin and tissue inhibitors of metalloproteinases, favoring cell spreading and anchorage-independent growth." (PMID 30103412, 2018).
tumor (continued). "Myc-induced downregulation of the microRNAs miR-26a and miR-101 leads to upregulation of their target Enhancer of Zeste Homolog 2 (EZH2) in ENKTL tumor tissue and cell lines." (PMID 29966370, 2018). "Taken together, our results provided an explanation for the aggressive nature of human tumors overexpressing Ezh2 through a mechanism that links Ezh2 to the key tumor suppressor PTEN." (PMID 29335012, 2018). "Although the oncogenic roles of EZH2 in many cancer types have been reported, the tumor suppressive roles of EZH2 were also identified." (PMID 29556394, 2018). "Pairs of never-smoked and smoking-associated patient samples 1Aa and 1Ab, 1Ag and 1Ah, and 1Ak and 1Al belonging to similar stage of disease and tumor grade displayed increased EZH2 expression in smoking ones." (PMID 29396474, 2018). "EZH2 has been shown to have both tumor suppressor and pro-oncogene properties depending on the cancer type." (PMID 30555699, 2018). "EZH2 overexpression is correlated with increased promoter methylation across tumor types in the Cancer Genome Atlas (TCGA)." (PMID 30469511, 2018). "The combination of BTZ/NM after neoadjuvant GSK126 treatment in carcinomas that homogeneously express Ezh2 has pro-apoptotic effects alongside modifications of the tumor microenvironment." (PMID 30487290, 2018). "KDM2B silencing is also reported to increase levels of tumor‐suppressing miRNA let‐7b, thereby downregulating EZH2 and reducing the entry into S‐phase and thus cancer growth." (PMID 29360266, 2018). "Inhibition of EZH2 expression and activity is associated with HMCL growth inhibition and decreased tumor load in a mouse model of MM." (PMID 30285865, 2018). "Cbx7, one of the core components of Cbx-PRC1, and Ezh2 can be a proto-oncogene or a tumor suppressor in a context-dependent manner." (PMID 29802243, 2018). "Our data demonstrate a dependence of CARM1-expressing cells on EZH2 activity, reflecting the silencing of EZH2 target tumor suppressor genes in a CARM1-dependent manner." (PMID 29434212, 2018). "Similar to the IPA analysis, GSEA identified upregulation of pathways related to ECM organization and Axon Guidance in Ezh2−/− tumours." (PMID 29959321, 2018). "Statistical analyses revealed that Ezh2 mRNA expression strongly correlated with the tumor size (P = 0.003), lymphatic invasion (P = 0.019), and TNM stage (P = 0.016), indicating that Ezh2 overexpression is associated with the clinical progression of human GC." (PMID 29335012, 2018). "As a nuclear protein, ARMC12 interacts with RBBP4 protein via the ARM domain to increase the formation of PRC2 complex and facilitate the EZH2 activity, which represses the transcription of downstream tumor suppressive genes." (PMID 30026490, 2018). "In our study, galectin-9 levels were positively correlated with those of the well-known oncogene EZH2 and were down-regulated by the tumor suppressor miR-22." (PMID 29316949, 2018). "It is interesting to note that EZH2 repression (and consequently H3K27me3 repression) induces osteogenic and myogenic differentiation and suppresses tumour formation." (PMID 29853899, 2018). "Given the evidence for the enzymatic gain-of-function of EZH2 in various tumor types, the development of pharmacological and dietary interventions affecting EZH2 has been an active area of investigation for the prevention and management of human malignancies." (PMID 28758948, 2017). "Consistent with previous studies, we found that EZH2 overexpression was associated with higher FIGO stage and tumor metastasis." (PMID 28620234, 2017). "Its oncogenic activity in cancer mainly depends on EZH2-mediatd epigenetic modification, such as DNA methylation and histone methylation, resulting in aberrantly silencing of tumor suppressive genes in cancer." (PMID 29141691, 2017). "Recent study shows that EZH2 activity is required for the growth of mouse DIPG tumor cells in vitro." (PMID 29118968, 2017).